CIITA (class II major histocompatibility complex transactivator)
Diseases named in the same sentence as CIITA in open-access papers (continued):
Sharing a sentence is not in itself a finding about the gene and the disease.
cancer (48 papers, 2004 to 2025). A tumor composed of atypical neoplastic, often pleomorphic cells that invade other tissues. "We observed that low expression of the autophagy-related protein MAP1LC3C in cancers is associated with decreased CIITA and HLA class II expression and with reduced immune cell infiltration." (PMID 39928678, 2025). "In conclusion, we show that reduced MAP1LC3C associates with cancers that display low infiltration of immune cells (“immune cold tumors”) and controls HLA class II expression through the regulation of CIITA." (PMID 39928678, 2025). "To further elucidate the genomic alterations of CIITA, we systematically assessed its mutation profile across diverse cancer types, with a particular focus on mutation frequency and classification." (PMID 40861816, 2025). "In LUAD, loss of CIITA reduced cancer cell-specific MHCII and transformed LUAD from anti-PD-1-sensitive to anti-PD-1-resistant." (PMID 35620481, 2022). "We further show that HDAC1 and HDAC2, but not LSD1, are responsible for RCOR2-dependent transcriptional suppression of CIITA in cancer cells." (PMID 40608411, 2025). "Intriguingly, cancer immunity cycle analysis indicated that CIITA scores were positively correlated with both the stimulatory and inhibitory regulatory activities across all stages of the immune cycle." (PMID 40861816, 2025). "RCOR2 activates Wnt/β-catenin signaling but suppresses CIITA/MHC-II signaling in cancer cells through two distinct epigenetic programs." (PMID 40608411, 2025). "Together, these findings indicate that RCOR2 specifically induces MHC-II silencing in cancer cells through suppression of CIITA." (PMID 40608411, 2025). "Further analysis revealed that CIITA expression levels in cancer cells was not uniform; interrogating the individual clusters revealed that CIITA was substantially expressed in only 5 of the 15 cancer cell clusters." (PMID 39025846, 2024). "Collectively, these findings highlight the critical importance of CIITA as a master regulator of MHC-II-associated gene expression, its deregulation in cancer cells, and the contributions of epigenetic mechanisms to pathogenesis." (PMID 38915093, 2024). "One study revealed that miR146b-5p and let-7f-5p both target CIITA in macrophages and in various cancer cell types." (PMID 38539461, 2024). "Representative examples of MHC-I and MHC-II players in liver cancer, such as B2M and CIITA, showed similar patterns as other cancer types, with heterogenous protein expression in tissue microarrays and low gene expression being predictive of poor survival." (PMID 38915093, 2024). "All MHC-II genes which were statistically significant in the bulk RNAseq DGE analysis also had a statistically significant correlation with CIITA expression within cancer cells in the snRNAseq data." (PMID 39025846, 2024). "Using a dataset of 594 CRC patients/samples from the TCGA Pan Cancer Atlas, we looked at the percentage of alterations present in HDAC2, CIITA, and B2M based on mutations, mRNA expression levels, structural variants, and amplifications." (PMID 37046620, 2023). "It is evident from the volcano plot that highly mutated genes MUC4, MUC16, CIITA, and ALK are mutated and overexpressed, of which ALK and CIITA are cancer census genes, whereas NCOR2 a transcriptional corepressor was mutated and downregulated." (PMID 37091785, 2023). "In zabadinostat-treated HCT116 cancer cells, treatment with the CIITA siRNA reduced the level of MHC class I HLA-A and -C but had less effect on HLA-B and -E." (PMID 36702861, 2023). "They found that loss of CIITA, a master regulator of the MHC-II pathway, decreased MHC-II expression in cancer cells and made the cells resistant to anti-PD1." (PMID 37501683, 2023). "It is of utmost importance that future investigations cast a wide net, encompassing diverse cancer types, to ascertain the deficit prevalence of CIITA expression and HLA-DM functions." (PMID 37454231, 2023).
cancer (continued). "We also analyzed CIITA expression in primary CRCs in TCGA data sets, which was increased in Fbw7 mutant cancers compared with Fbw7 WT tumors." (PMID 35225231, 2022). "(F) CIITA expression in primary cancer samples from TCGA COADREAD data sets that have WT Fbw7 (n=297) and mutated Fbw7 (n=43)." (PMID 35225231, 2022). "CIITA positively regulates the expression of class II major histocompatibility complex and is often found to be methylated in cancer cells." (PMID 35096000, 2021). "Another factor involved in the expression of CIITA in cancer has been identified in pediatric glioblastomas." (PMID 33499042, 2021). "The presence of H3K27me3 suppresses CIITA expression, thus reducing the CIITA expression thereby reducing MHC II molecules on the cancer cells’ surface of cancer cells and allowing cancer cells to evade the immunity network." (PMID 34884658, 2021). "Twelve genes were frequently targeted in both cohorts independently, including BCL2, BCL6, BCL7A, CD74 and CIITA, all listed as oncogenes in the Cancer Gene Census and known to be involved in lymphomagenesis." (PMID 25903198, 2015). "In conclusion, both isoforms in carcinoma determine a comparable CIITA activation and MHC II transcription, with only p42 isoform being able to block MHC II protein synthesis through a mechanism which is currently under investigation." (PMID 26081906, 2015). "Studies investigating deficient CIITA and MHC class II expression in various cancer cell lines have identified epigenetic modifications that result in transcriptional silencing." (PMID 24475282, 2014). "In addition to IFN-γ response-associated genes (JAK1, STAT1 and STAT3), CIITA, a master regulator of MHC-II gene expression, was highly expressed in MHC-II+ cancer cells." (PMID 41281745, 2025). "Taken together, the results suggest that antibodies blocking MHC-II and/or small molecular drugs inhibiting CIITA may be effective immunotherapeutic in patients with certain cancers and might also increase the efficacy of checkpoint inhibitors." (PMID 39470607, 2024). "Whereas, CIITA being an MHC II transactivator, mutations might cause hindrance in MHC II expression and cancer immunity." (PMID 37091785, 2023). "CD4+ T-cell help for CD8+ T cells is crucial in the generation of robust effector and memory CTL responses: immunologic protection of CIITA transfected cells is due to the generation of primed CD4+ T cells providing help for the generation of cancer antigen-specific CTL effectors." (PMID 37565053, 2023). "Finally, the IFN-γ-responsive pIV of cIIta is silenced in fetal trophoblast cells and in cancer cells by DNA methylation." (PMID 33072127, 2020). "Importantly, capacity to reject the tumors and/or strongly retard their growth was directly related to the amount of CIITA-driven MHC class II molecules expressed on the cancer cell surface." (PMID 31417570, 2019). "Thus, downregulation of CIITA and MHC-II-associated gene expression may be a common mechanism of immune escape in cancer cells." (PMID 38915093, 2024). "Whether expressed constitutively or induced by interferon-γ, expression of MHC class II molecules is regulated via coactivator class II transactivator (CIITA); moreover, suppression of their expression is one mechanism by which cancer cells escape host immunity." (PMID 14970863, 2004). "Consistently, RCOR2 inversely correlated with CIITA and most MHC-II heavy chain genes in 1,156 cancer cell lines and 1,210 pan-cancers." (PMID 40608411, 2025). "Protein levels of CIITA and MHC-II molecules were also elevated in RCOR2-depleted cancer cells following IFN-γ treatment and in PyMT tumors, as shown by immunoblot, flow cytometry, and/or immunostaining assays." (PMID 40608411, 2025).
cancer (continued). "Silencing the expression of CIITA, the master regulator of MHC Class II, in cancer cells that express MHC II in vivo blunted the response to anti-PD-1, whereas expressing CIITA in resistant cells sensitized tumors to anti-PD-1 therapy." (PMID 40805126, 2025). "Having seen a moderate correlation between CIITA and IRF1 in the bulk RNAseq data, we examined this in the snRNAseq, but found a more modest correlation between CIITA and IRF1 expression within cancer cells (R = 0.26, p < 0.001, CS-CORE)." (PMID 39025846, 2024). "We also identified cancer cell heterogeneity, with only a subset of cancer cells expressing MHC-II, likely driven by inducible CIITA expression, and that these cells are rare in cancers with early WGD." (PMID 39025846, 2024). "Similarly, using RNA-seq data, we found that a lower expression of APM-related genes, including B2M, CIITA, ERAP2, TAP2 and TAPBPL, was also associated with a shorter PFS, reflecting the increasing interest in APM biomarkers for clinical outcome and immune escape in cancer." (PMID 37799721, 2023). "In specific, TIS is referred to as an 18‐gene signature (CCL5, GZMK, CD3D, CD3E, CD2, HLA‐DRA, IL2RG, NKG7, CIITA, CXCR6, LAG3, TAGAP, HLA‐E, CXCL13, IDO1, CXCL10, STAT1, and GZMB), which was related to the response to ICIs in various cancers." (PMID 37434432, 2023). "Several studies have shown that artificial overexpression of CIITA, and thus of MHC-II, in cancer cells leads to increased antitumoral response." (PMID 33499042, 2021). "All these genes have already been associated with hypermutated regions in BCLs (BCL2, BCL6, BCL7A, BIRC3, CIITA and ST6GAL1) or listed in the Cancer Gene Census (BCL2, BCL6, BCL7A, BIRC3, CIITA, IGLL5 – in the IGL@ locus – and LPP)." (PMID 25903198, 2015). "This cross-cancer commonality strongly suggests that CIITA is not merely a context-specific regulator, but rather serves as a core modulator of immune homeostasis." (PMID 40861816, 2025). "By searching differentially expressed genes involved in interferon signaling pathways from our RNA-Seq dataset, we found that a family of MHC-II heavy chain genes and their transcriptional coactivator CIITA were repressed by RCOR2, which was validated in multiple cancer cell lines by RT-qPCR assay." (PMID 40608411, 2025). "Multiple studies have demonstrated that many cancer cell lines are not class II inducible by IFNγ due to transcriptional silencing of CIITA." (PMID 37565053, 2023). "Interestingly, CIITA expression and protein levels increased upon zabadinostat treatment; for example, in NBE1 and BEAS2B cells, in addition to the cancer cell line HCT116." (PMID 36702861, 2023). "CIITA-transfected cancer cells are readily rejected unlike their class II negative counterparts and massively infiltrated by immune effector cells." (PMID 37565053, 2023). "The selected SNVs and indels potentially affected amino acid sequences that were not located in either genes related to cancer (other than the HLA-A and CIITA genes) or predicted off-target regions." (PMID 35755947, 2022). "As could be expected, CIITA is a major target for cancer immune escape mechanisms, and ectopic expression of CIITA and NLRC5 present promising avenues in cancer vaccination strategies." (PMID 33499042, 2021). "Finally, as CIITA profoundly affects HTLV-1 replication by interacting and inhibiting the function of HTLV-1 Tax-1 molecule, the major viral product associated to the virus oncogenicity, we also put forward the hypothesis of CIITA as counteractor of HTLV-1-mediated cancer initiation." (PMID 31783769, 2019). "In the present study, canonical NF-κB signalling was continuously attenuated in the cancer group during MoDC differentiation, likely resulting in the transcriptional suppression of CIITA and MHC class II genes and the further impairment of antigen presentation." (PMID 28350008, 2017).
infection (37 papers, 2010 to 2025). The state of being infected such as from the introduction of a foreign agent such as serum, vaccine, antigenic substance or organism. "The pathway analysis based on the KEGG database revealed that many immune-related and infection-related pathways were enriched, also suggesting that insufficiency of B2M and CIITA genes may make pigs susceptible to pathogenic microorganisms." (PMID 35573408, 2022). "In human GSC lines (P3NS and T16NS), CIITA mRNA and protein were detected at 72 h post‐infection with both Ad‐CIITA and Ad‐CIITA mutant." (PMID 39535369, 2025). "Firstly, irrespective of when Tax expression occurs (either during initial infection or a Tax burst in the latency phase), induction of Tax leads to increased CIITA expression." (PMID 36300109, 2022). "Further, silencing of HDAC1 resulted in the reversion of CIITA expression indicating that histone H3 deacetylation is an important player in establishing parasite within the host cell at an early stage of infection." (PMID 35433496, 2022). "RNA-seq transcriptomic indicated that CIITA is down regulated during EBV primary infection, and we confirmed that by RT-qPCR comparing 21 day LCL to primary B-cells from the same donor." (PMID 34352044, 2021). "CIITA-expressing U2OS cells were also highly resistant to infection by high titers of native EBOV, showing reduced reporter gene expression, cell death, and plaque formation." (PMID 32855215, 2020). "A study showed, that infection of mycobacterium bovis bacillus calmette-guérin regulates the epigenetic changes at class II transactivator (CIITA) promoter via induction of expression of iNOS and miR-150 through the recruitment of the transcription factor." (PMID 31954402, 2020). "The class II major histocompatibility complex (MHC-II) transactivator gene (CIITA) is downregulated at the chronic stage of the infection." (PMID 31555289, 2019). "The expression of both TRIM22 and CIITA mRNAs was indeed promptly upregulated after 18 h of cell stimulation of MDM with M1 cytokines before infection." (PMID 30250078, 2018). "The expression of CIITA mRNA was also investigated in vivo at 3 and 6 h after infection, with splenic DCs derived from S. suis-infected mice showing low levels of CIITA compared to naïve mice." (PMID 29899744, 2018). "Our data show that the H6 promoter was more efficient than SP to drive CIITA expression and that CIITA can enhance the levels of the gag/pro and env gene products only when infection is performed by FP single recombinants." (PMID 29385169, 2018). "This occurs only when the CIITA gene is driven by the H6 promoter and infection is performed with FP single recombinants." (PMID 29385169, 2018). "In this study, CIITA expression in both infection groups up-regulated, compared with the healthy controls." (PMID 26252489, 2015). "The early infection kinetics were similar in both mouse strains; however, at all time points from day 12 onwards, CIITA−/− mice manifested a significantly higher degree of liver infection than wild-type mice." (PMID 24466045, 2014). "Indeed Ad‐CIITA infection of primary GB cells resulted in robust MHC‐II expression at the surface of infected cells." (PMID 39535369, 2025). "Furthermore, CIITA inhibited infection mediated by glycoproteins (GPs) from a range of EBOV species—including Sudan, Zaire, and Reston—as well as by those from the distantly related filovirus Marburg virus." (PMID 32855215, 2020). "B. abortus infection induced up-regulation of CIITA mRNA after 72 h post-infection." (PMID 32629846, 2020). "Proinflammatory IFN/cytokine stimulation may increase levels of CIITA in the microglia, thereby protecting these cells from infection with SARS-CoV-2." (PMID 33235189, 2020).
infection (continued). "We confirmed this finding by histological staining of CD8+ T cells in liver sections of infected mice, showing greatly decreased numbers of CD8+ T cells in CIITA−/− livers at day 12 and equally low CD8+ T-cell numbers in wild-type and CIITA−/− livers at day 15 after infection." (PMID 24466045, 2014). "Importantly, quantification by real-time PCR indicated that infection with T. gondii abolished the IFN-γ-induced histone H4 acetylation of CIITA pIV chromatin by more than 90% (p = 4×10−7; Student's t-test)." (PMID 22275866, 2012). "Similarly, the defective up-regulation of CIITA as observed after infection of IFN-γ-treated MΦ with T. gondii was also dose-dependently diminished by sodium butyrate and MS-275." (PMID 22275866, 2012). "Several Nod-like receptor (NLR) family genes (nucleotide-binding oligomerization domain (NOD) 1, NOD2, NLRP2, NLRP3 and class II trans-activator (CIITA)) which act as intracellular sensors to detect cytosolic microbial components and "danger" signals were elevated upon infection." (PMID 21110886, 2010). "Therefore, we hypothesized that the global levels of H3 acetylation would decrease on the CIITA promoters on infection under stimulated condition." (PMID 35433496, 2022). "Because IFNγ signaling significantly increases MHC-II expression via the IRF-1/CIITA axis, with peak serum IFNγ levels observed at 16 days post-MHV68 infection, the expression of MHC-II by germinal center B cells was measured next." (PMID 41263556, 2025). "Our analysis revealed differential expression patterns for several immunological genes, including CD94, CD19–2, CD23, IL-7, and CIITA, during LF2384 and LF2350 infection." (PMID 38826374, 2024). "Consistent with the results obtained in CIITA−/− mice, we found that CD4+ T cell-depleted mice, at day 18 after infection, still manifested significantly higher viral titers in the liver, whereas control IgG-treated animals had cleared the virus." (PMID 24466045, 2014). "Following the standard PBMC infection protocol with GFP-KSHV (Bac36) we investigated the CIITA pIII and pIV promoter and six subtypes of HLA along with KSHV infection within 7 days." (PMID 24204280, 2013). "TAF7 was recently demonstrated to also regulate the acetyl transferase activity of CIITA, which is the key factor in TAF1-independent transcription of MHC class I and II in response to infection." (PMID 22043290, 2011). "Tat competes with the co-activator CIITA for binding to P-TEFb and this leads to down regulation of MHC class II genes during infection; a clear advantage for the virus." (PMID 20808803, 2010). "Infection with an AdV carrying a mutant form of CIITA with a single amino acid substitution resulted in cytoplasmic accumulation of CIITA without subsequent MHC‐II expression." (PMID 39535369, 2025). "In P3 organoids, a viral multiplicity of infection (MOI) between 25 and 100 led to strong ectopic expression of CIITA and HLA‐DRα at 72‐post‐infection, without a major effect on tissue structure." (PMID 39535369, 2025). "CIITA was upregulated by LASV LF2384 infection, whereas LF2350 infection led to its downregulation." (PMID 38826374, 2024). "A reversal in CIITA expression and decreased parasite load was observed with BRG1 overexpression, thus, suggesting BRG1 is a potential negative regulator for the survival of intracellular parasites in an early phase of infection." (PMID 35433496, 2022). "Additionally, the Mpg-infected BMDCs showed higher levels of the two MHC II-related targets, CIITA and H2DMb, than the BCG-infected BMDCs (about five-fold increase compared with the BCG-infected BMDCs 24 hours after infection)." (PMID 29123166, 2017). "Interestingly, in addition to the CIITA pIII and pIV transcripts, the reduced level of HLA-DQβ upon KSHV de novo infection was consistent with increased expression of LANA in a dose-dependent manner." (PMID 24204280, 2013).